IL1B (interleukin 1 beta)
Diseases named in the same sentence as IL1B in open-access papers (continued):
Sharing a sentence is not in itself a finding about the gene and the disease.
immune dysfunction (83 papers, 2011 to 2025). "IL-1β, generated through inflammasome activation, plays a key role in amplifying immune responses and is implicated in the pathogenesis of several immune disorders." (PMID 40564127, 2025). "The inflammaging-associated immune dysfunction include elevated basal levels of IL-6, which transforms monocytes into antigen presenting cells to produce IL-1β and IL-23." (PMID 37266014, 2023). "The activation of pro-inflammatory cytokines, such as TNF-α, IL-1β, and IL-6, in intestinal inflammatory cells can cause a cascade of intestinal inflammation that leads to local inflammation and immune system disorders." (PMID 34348563, 2021). "IL-1β is an important proinflammatory cytokine that has been associated with the pathogenesis of vascular and immune diseases." (PMID 32047809, 2020). "IL-1β and IL-18 are pro-inflammatory cytokines that cause complex immune diseases." (PMID 35042538, 2022). "The cited study revealed inflammation of the small intestine in pregnant sows as well as changes in newborn piglets where immune dysfunctions and increased expression of the genes encoding proinflammatory cytokines IL-6, IL-1α, IL-1β, and TNFα were observed in the small intestine." (PMID 32471145, 2020). "Fact: Endometriomas are associated with elevated levels of pro-inflammatory cytokines (e.g., IL-6, IL-8, IL-1β) and immune dysfunction, contributing to disease progression." (PMID 40217598, 2025). "From our data, K88 significantly upregulated proinflammatory cytokine expression (e.g., IL-1β, TNF-α, IFN-γ) in the ileum, which possibly caused immune disorders in the ileum, exacerbated inflammation, and damaged ileum tissue." (PMID 39857392, 2025). "Preparations from Hericium coralloides and T. versicolor rebalanced cytokine profiles in immune cells from older adults, reducing IL-5 and IL-13 while adjusting IL-1β, IL-6, and interferon levels—an effect relevant to age-related immune dysfunction." (PMID 41488566, 2025). "IL-1β is a pro-inflammatory cytokine that that induces pain, inflammation, and auto-immune disorders." (PMID 38310564, 2024). "Extracellular HMGB1 upregulates the expression of pro-inflammatory factors including IL-6, IL-1β, IL-12, and TNF-α through the activation of TLR2/4, causing cytokine storms, immune disorders, and severe apoptosis in the spleen, thymus, and bursa of Fabricius." (PMID 38474071, 2024). "TET2 has various mechanisms in neoplastic and immune diseases and downregulates the expression of inflammatory cytokines IL-6 and IL-1β through recruiting HDAC enzymes for histone deacetylation in innate myeloid cells and macrophages." (PMID 39659792, 2024). "These EDCs disrupt the normal functioning of hormones in males and elevate the levels of pro-inflammatory cytokines such as IL-1b, IL-2, IL-6, IL-10, and IL-17A, leading to immune system disorders." (PMID 39636940, 2024). "PGE2 is the most abundantly detected PG in various tissues and has been shown to promote the production of various pro-inflammatory factors (such as IL-1β, IL-6, and IL-12) in immune diseases." (PMID 36937256, 2023). "Purpurin played an anti-inflammatory role by inhibiting IL-6, TNF-α, and IL-1β and increasing IL-10, and regulated immune disorder by decreasing the CD4+/CD8+ ratio and increasing the FOXP3 level." (PMID 36615560, 2023). "The upregulation of NEAT1 has been shown to promote the release of several inflammasomes (NLRP3, NLRC4, and AIM2) and pro-inflammatory cytokines (CXCL10, IL-6, and IL-1β), resulting in an immune response in inflammatory and immune diseases." (PMID 35127819, 2021). "The study found that the released HMGB1 formed complexes with pro-interleukin-1-beta (pro-IL-1β) in both human and mouse plasma, and this heterocomplexes were able to induce immune dysfunction in LBI." (PMID 34721407, 2021). "The activation of IL-1β-dependent intracellular signaling plays crucial role in immune diseases and responses." (PMID 32727543, 2020).
immune dysfunction (continued). "The imbalance of proinflammatory cytokines, such as IL-6, TNF-α, IL-1β, and IL-10, was demonstrated that contributed to immune dysfunction and also mediated inflammation of the tissues and organ damage in SLE." (PMID 31886314, 2019). "The release of Damage-Associated Molecular Patterns (DAMPs), such as HMGB1, and cytokines (e.g. IL-1β) creates an environment of immune dysfunction often leading to end organ failure and death." (PMID 29601597, 2018). "We now find HMGB1/IL-1β complexes in human and mouse plasma, and identify a synergistic role of HMGB1/IL-1β complexes in post-burn immune dysfunction." (PMID 29601597, 2018). "Immune diseases are often treated by blocking the expression of IL-1β clinically." (PMID 37152746, 2023). "The abnormal expression of inflammatory factors such as TNF-α, IL-1β, IL-6 and IL-17 might affect the pathophysiological processes such as intestinal flora imbalance and immune dysfunction in DC patients." (PMID 36998438, 2023). "Antibiotics induced immune dysfunction resulted in disproportionate release of cytokines and increased intestinal mucosal inflammation, including higher expression levels of IL-1β, IL-6, and TNF-α, which were considered as common biomarkers in various inflammatory conditions." (PMID 36726819, 2022). "Patients in the UTI group may have had immune dysfunction, thus leading to a significant increase in the serum levels of IL-1β and IL-6." (PMID 35531475, 2022). "However, chronic overexpression of IL-1β has been related to multiple immune diseases, including T2DM." (PMID 34754627, 2021). "Since B[a]P is known to induce immune dysfunctions and microalgal extracts are involved in anti-inflammatory activities, their influence was next studied on the expression of several pro-inflammatory cytokines such as IL-8 and IL-1β." (PMID 31861403, 2019). "Therefore, we screened pro-inflammatory cytokines IL-1β, TNF-α, and IL-6, which cause immune disorders and amplify inflammation, as well as anti-inflammatory cytokine IL-10." (PMID 31500342, 2019). "Once LPS is released into the blood system, it can trigger monocytes and phagocytic cells to secrete large amounts of various pro-inflammatory cytokines such as TNF-α, IL-6, IL-1β and various others that contribute to the pathophysiology of septic shock and other immune diseases." (PMID 30065898, 2018). "Given that IL-1β is an essential component of the host defense, they hypothesized that insufficient IL-1β or excessive IL-1RA results in systemic immune dysfunction." (PMID 26507130, 2015). "Overexpression of IL-1β and TNF-α can lead to immune dysfunction in the body, resulting in host inflammation." (PMID 40342298, 2025). "Additionally, multiplex cytokine analysis revealed significant elevations in Eotaxin, IL-1β, IL-4, IL-6, IL-8, MIP-1α, and TNF-α in SZ patients, whereas IFN-γ, IL-9, IL-1ra, IL-13, MCP-1, MIP-1β, and RANTES were reduced (p < 0.05), indicating a complex immune dysfunction associated with SZ." (PMID 40761785, 2025). "The significant inhibition of M. comosus extracts against IL-1β, TNF-α and IL-6 makes it a potential therapeutic target against multiple immune disorders." (PMID 38310564, 2024). "Dysregulation of the cytokine network further supports the immune dysfunction in ME/CFS, with elevated levels of TNF-α and IL-1β observed in ME/CFS patients." (PMID 39845969, 2024). "Increased levels of proinflammatory mediators from M1-type macrophages lead to inflammation and immune disorders, such as TNF-α, IL-6, and IL-1β." (PMID 37035757, 2023). "The increased abundance of inflammation-related microbiota resulted in immune disorders and intestinal barrier dysfunction by upregulating TLR2/4/5 and promoting the release of IL-1β and TNF-α." (PMID 33329010, 2020).
immune dysfunction (continued). "As one of the main controllers of the immune response, many pro-inflammatory cytokines such as IL-6, IL-1β, and TNF-α have been reported to respond to stress and immune disorders, and IL-6-related pathways also play a key role in regulating acute heat stress." (PMID 33233727, 2020). "Recently, a number of biologic agents targeting inflammatory cytokines, such as IL-6, IL-1β and TNF-α have been developed and used as therapeutics for RA and other immune disorders." (PMID 27070121, 2016). "Decreased levels of IL-1β inhibit msu-induced activation of NLRP3 inflammatory vesicles, impede maturation and secretion of inflammatory cytokines, thereby reducing the recruitment of neutrophils and other cells and regulating immune disorders." (PMID 36313318, 2022). "Canakinumab is a high-affinity human anti-IL1 β monoclonal antibody of the IgG1/k isotype developed for the treatment of immune disorders, and it is highly specific for IL-1β and does not interfere with other IL-1-activated pathways." (PMID 27590627, 2016). "CTLA4, a negative regulator in auto-immune diseases, participates in the pathways of CAMs and T cell receptor signalling contributing to autoimmune tissue destruction and it might exert a down-regulatory effect on TNF-α, TGF-β, IL1-β and IL16 production." (PMID 29401671, 2018).
kidney disease (83 papers, 2012 to 2025). "Proinflammatory interleukin-1 beta levels and interleukin-1 beta gene polymorphism is also associated with the risk of development and progression of kidney disease in T2DM." (PMID 36289848, 2022). "The activation of IL-1R, the receptor of IL-1β, reportedly limits necroptosis in certain kidney diseases." (PMID 40359428, 2025). "Inhibition of IL-1β can have protective effects on renal disease progress by reduced mRNA expression of neutrophil gelatinase–associated lipocalin as a kidney injury marker and fibrosis." (PMID 37275762, 2023). "Pro-inflammatory cytokines, particularly IL-1β, produced by inflammatory cells, tend to increase during renal disease." (PMID 37521462, 2023). "Activation of NLRP3 inflammasome contributes to the maturation and release of proinflammatory factors such as IL-1β and IL-18, which is a vital component of inflammatory response and plays an important role in the progression of kidney diseases." (PMID 36212965, 2022). "The pathophysiological mechanisms of kidney diseases are associated with factors that predispose to redox imbalance and the generation of inflammatory mediators, including ROS, TNF-α and IL-1β." (PMID 36077498, 2022). "In an anti-MPO antibody-induced experimental model of NCGN, a protective role of DPPI in kidney disease was demonstrated with a local decrease in inflammatory cytokines, especially IL-1β." (PMID 35457026, 2022). "Concurrent to our study, another study reported that IL-6 has a more active role in renal diseases than IL-1β." (PMID 35743930, 2022). "Many inflammatory factors play a critical role in renal diseases, such as TGF-β1, TNF-α, and IL-1β; the activation and proliferation of intrinsic cells were resulted by them, and then, the occurrence and progression of renal diseases is aggravated." (PMID 33312224, 2020). "Most recently, the inhibition of IL-1β by using a monoclonal antibody in diabetic db/db mice with progressive kidney disease was demonstrated to reduce the expression of renal damage markers and to attenuate GFR decline." (PMID 33139635, 2020). "Interleukin, the multifunctional inflammatory cytokines are closely associated with various renal diseases and the injury of kidney residential cells, such as IL-6, CXCL8, IL-1β, IL-2 and IL-4." (PMID 32765640, 2020). "TNF-α, an important regulatory factor, which can promote the production of IL-6, IL-1β, and other cytokines, participates in inflammation, oxidative stress and damage in various renal diseases." (PMID 32765640, 2020). "NLRP3 inflammasome activation and subsequent IL-1β maturation have increasingly been reported to participate in the pathogenesis of various kidney diseases." (PMID 31616439, 2019). "The roles of IL-1β and IL-18 in renal disease are well known, but the importance of inflammasomes in their activation has not been investigated." (PMID 29929501, 2018). "Our data suggest that serum IL-18 and IL-1β have different clinical implications in SLE, with IL-18 being potentially associated with active renal disease." (PMID 29930551, 2018). "In the present study, IL-1α and IL-1β were higher expressed in surviving dogs with all types of renal diseases compared to healthy dogs." (PMID 26824356, 2016). "There is a better understanding of the role of IL-1 and IL-18 in renal disease, although the importance of the inflammasome in the activation and secretion of IL-1β and IL-18 has only been investigated recently." (PMID 24450291, 2014). "In active renal disease patients, the IL-1β levels were positively correlated with SLEDAI score (r = 0.33, P < 0.001) compared with TNF-α (r = 0.18, P = 0.001) and IL-6 (r = 0.11, P = 0.01)." (PMID 25548434, 2014). "Therapeutic interventions that modulate this pathway are being developed, and the functional significance of the inflammasome and the IL-1β/IL-18 axis in renal disease is of growing interest." (PMID 24450291, 2014). "Increasing evidence has validated the role of IL-1β in kidney diseases." (PMID 40729113, 2025).
kidney disease (continued). "The anti-inflammatory effect of ARB could be more potent than that of ACEis; for example, ramipril, an ACEi, increases IL-1β and IL-10 in patients with kidney diseases." (PMID 35517809, 2022). "Patients with renal disease have elevated circulating levels of IL-1β." (PMID 35663044, 2022). "Similar effects have been attributed to IL-1β in human and experimental kidney diseases." (PMID 36077498, 2022). "TNF-α/IL-1β induces Ca2+ influx from the extracellular space and Ca2+ release from intracellular stores, leading to ROS generation and cell damage in several kidney diseases." (PMID 36077498, 2022). "In addition to IL-1β, NLRP3 inflammasome can also trigger IL-18 maturation, which is associated with the pathogenesis of various kidney diseases." (PMID 32028746, 2020). "Our data also indicate a strong association between serum IL-18, though not IL-1β, with renal disease activity in SLE." (PMID 29930551, 2018). "Elegant studies from the Fernandes laboratory have related the delayed onset and decreased severity of renal disease exhibited in fish oil-fed NZBWF1 mice to reduced IL-1β, TNF-α, TGFβ1, ICAM-1 and fibronectin expression and increased expression of antioxidant enzymes." (PMID 27513935, 2016). "Tff3, Vgfa, Vgfb, Vgfc, Il1b and Lgals3 were not differentially expressed in the present study even though they have been implicated in kidney disease." (PMID 26673451, 2015). "To determine whether the inflammasome was activated in proteinuric kidney disease, we first detected the intensity and distribution of caspase-1, IL-1β and IL-18 staining which were the markers of inflammasome activation in the human renal biopsies." (PMID 23977286, 2013). "Although based on in-vitro studies, NLRP3 inflammasome may have a role in the pathogenesis of renal diseases via overexpression of proinflammatory cytokines including IL-1β and IL-18, several pieces of evidence show that the NLRP3 effect may be independent of pro-inflammatory cytokine production." (PMID 34904012, 2021). "Several reviews have highlighted its effects on renal inflammation and fibrosis, elucidating its impact on inflammatory factors such as TNF-α, IL-1β, IL-6, and the TGF-β-Smad pathway, which contribute to fibrosis during kidney disease progression." (PMID 40442892, 2025). "CD68 serves as a marker for macrophages and plays a significant role in the development of numerous renal disorders, especially when pro-inflammatory cytokines such as TNF-α and IL-1β are present." (PMID 40529491, 2025). "It has been determined that pro-inflammatory cytokines and chemokines such as TNF-α, IL-1β, IL-6, IL-8, and MCP-1 are involved in the development of kidney diseases." (PMID 32028746, 2020). "The elevation of pro-inflammatory cytokines such as IL-1β, IL-6 and TNF-α is common in CKD (Furuichi, Kaneko & Wada, 2009) and has been used as a predictor of mortality in patients with kidney disease." (PMID 31275747, 2019). "The glomerular filtration rate (GFR) seems to be unaffected by acute or subchronic IL-1β administration to normal rats, while impact of the cytokine on GFR in kidney disease may be multifactorial and requires further investigations." (PMID 40486517, 2025). "This further supports our murine data suggesting involvement of these pathways in promoting sex-biased differences in kidney disease in the absence of IL-1β." (PMID 37261358, 2023). "Decreased IL-1β expression in the kidneys following SPI and SPIEE intake may be an important factor in preventing kidney disease progression." (PMID 35448517, 2022). "In addition, levels of IL-1α, IL-1β TNFα, INFγ, IL-2 and IL-10 were elevated in the sera of CKD compared to sham, suggesting that the chronic state of renal disease affects the inflammatory network." (PMID 29889834, 2018). "Dogs from all groups of renal diseases showed elevated expression of IL-1α, IL-1β, IL-10, TGF-β and iNOS, a pattern that may therefore be considered the signature for canine renal disease." (PMID 26824356, 2016).
kidney disease (continued). "Moreover, oxidized albumin in kidney disease patients is independently correlated with higher plasma levels of transforming growth factor beta (TGF-β1), tumor necrosis factor (TNF-α), and interleukin (IL)-1β and IL-6." (PMID 33800425, 2021). "Although we did not measure these cytokines (e.g., IL-1β and TNF-α), it was proposed that those cytokines concomitant with elevated serum ferritin might be considered to contribute to kidney disease progression." (PMID 37880328, 2023). "Blockade of IL-1β, the end product of an activated NLRP3 inflammasome, could not mitigate kidney diseases." (PMID 37685978, 2023). "However, blockade of IL-1β, the end product of the activated NLRP3 inflammasome, failed to mitigate kidney disease, whereupon interest concerning inflammasome-independent NLRP3 increased." (PMID 31694192, 2019). "In this systematic review, inflammatory markers were evaluated in kidney disease, showing a significant reduction in the levels of renal NF-κB, serum immunoglobulins, renal ED-1+ cells, and urinary MCP-1 following Propolis supplementation; while IL-1β levels did not change significantly." (PMID 35057819, 2022).